SNORD13E (small nucleolar RNA, C/D box 13E)
Gene: Small nucleolar RNA gene on chromosome 15 (65,696,833 to 65,696,936, reverse strand). Ensembl gene ENSG00000238311.
Gene Ontology:
Biological process: RNA processing
Cellular component: nucleolus
Homologues: Orthologues: chimpanzee SNORD13E (98% identical), macaque SNORD13E (94% identical). Paralogues in human: SNORD13D (89% identical), SNORD13 (88% identical), SNORD13P3 (87% identical), SNORD13P1 (82% identical).